PTGDR (prostaglandin D2 receptor)
Diseases named in the same sentence as PTGDR in open-access papers (continued):
Sharing a sentence is not in itself a finding about the gene and the disease.
Pleural effusion (1 paper, 2021). The presence of an excessive amount of fluid in the pleural cavity. "Interestingly, Ooki and colleagues, determined the clinical utility of a set of six genes, including CDO1, HOXA9, AJAP1, PTGDR, UNCX, and MARCH11, for predicting LC diagnosis not only in serum samples but also in pleural effusions and ascites." (PMID 33937034, 2021).
type 1 diabetes mellitus (1 paper, 2022). A chronic condition characterized by minimal or absent production of insulin by the pancreas. "Finally, the CPE gene was suggested to influence Type I diabetes mellitus whereas GRID2 and PTGDR are responsible for neuroactive ligand-receptor interaction." (PMID 36011330, 2022).
tumor (149 papers, 2012 to 2026). "More specifically, PGD2 plays a pivotal role in signaling through its associated aixes, such as PGD2 ∼ SLCO2A1 and PGD2 ∼ PTGDR, suggesting potential metabolic implications in tumorigenesis, tumor invasion and metastasis." (PMID 40474982, 2025). "Tumor molecular profiles showed few associations with clinicopathological variables, and these included downregulation of PTGDR and PTGS1 in older patients, overexpression of PTGER2, and hypermethylation of PTGS2 in right side tumors as compared with left colon." (PMID 26207152, 2015). "Collectively, these findings suggest that both PTGDS and PTGDR are downregulated in LUAD tumor tissues, with their expression patterns further substantiated in corresponding cell types." (PMID 40474982, 2025). "The RT-qPCR results showed that PTGDS and PTGDR mRNA levels were lower in tumor tissues than in normal tissues." (PMID 40474982, 2025). "To confirm the expression patterns of PTGDS and PTGDR in tumor and normal tissues, we conducted a series of preliminary experiments using five pairs of LUAD tumor and distant normal lung tissues." (PMID 40474982, 2025). "Other pairs of co-expressed genes encoding prostanoid receptors were as follows: PTGIR-PTGER2, r = 0.72 − 0.75, TGCT tumor; PTGER4-PTGER2, 0.68–0.78, SKCM tumor; PTGDR-PTGER2, r = 0.66 − 0.74, SKCM tumor; PTGDR-PTGER3, 0.59–0.67, PAAD tumor." (PMID 35453789, 2022). "In summary, our investigation indicated that the risk model composed of PTGDR, PNOC and CCL23 has potential to predict prognosis and evaluate the tumor immune microenvironment in HPBC patients." (PMID 35665772, 2022). "The results support an interpretation that PGD2 is a tumor-suppressing molecule, acting through PTGDR." (PMID 24729479, 2014). "Finally, it is confirmed that the expression of PTGDS in fibroblasts and PTGDR in NK/T cells was downregulated at both the mRNA and protein levels in retrospectively collected paired tumor samples." (PMID 40474982, 2025). "We found that the mRNA levels of PTGDS and its receptor prostaglandin D2 receptor (PTGDR) were downregulated in tumours with larger size, higher stage, and higher histological grade, suggesting that PTGDS could serve as a protective factor." (PMID 32047563, 2020). "Three additional genes, BCL2, PRIMA1, and PTGDR showed hypermethylation only in tumour samples." (PMID 26482433, 2015). "The result supports an interpretation that PTGDR mediates tumor inhibition by PGD2 in these mice." (PMID 24729479, 2014). "However, tumor suppression by PGD2 was more clearly mediated by receptor PTGDR in our experiments." (PMID 24729479, 2014). "Firstly, relative genes involved in PGD2 signaling axis, HPGDS, PTGDS, PTGDR and SLCO2A1, were all significantly lower expressed in tumor lung tissue compared to normal in TCGA-LUAD cohort." (PMID 40474982, 2025). "The expression of PTGDS, PTGDR and SLCO2A1 also shows a decreasing trend across normal lung, tumor lung, and metastatic brain tissues, as well as in early and advanced stages and at different differentiation levels." (PMID 40474982, 2025). "For those genes deregulated after OOS treatment, PTGDR and SMARCA2 turned out to be more expressed in AML than in any other tumor type, conversely, SERPINE1 was less expressed in AML than in most other tumor types." (PMID 31091680, 2019). "Here, we show that knockouts of Ptgdr increased tumor numbers in ApcMin/+ mice, indicating that PGD2 and PTGDR act to suppress tumors." (PMID 24729479, 2014). "Furthermore, the PTGDR agonist, BW245C, reduced tumor growth." (PMID 24729479, 2014).
cancer (118 papers, 2012 to 2025). A tumor composed of atypical neoplastic, often pleomorphic cells that invade other tissues. "Of note, the methylation levels of PTGDR and ZNF135 genes were substantially higher in cancers when compared to precancerous tissues." (PMID 37405952, 2023). "PTGDR, PTGDR2, PTGER1, PTGER3, and PTGFR genes have the median expression value of about 1 FPKM (Fragments Per Kilobase Million), while other genes are expressed in the range of 1–5 FPKM, regardless of cancer specificity." (PMID 35453789, 2022).
kidney (1 paper, 2018). "Similarly to specific basophil depletion, blockade of both PTGDR in sick Lyn−/− animals decreased their autoantibody titers, their TH2 bias, and consequent glomerular immune complex deposition and kidney inflammation." (PMID 29463843, 2018).
PTGDR also shares sentences with these, for which no sentence is quoted: glioma (31 papers); gastric cancer (22); hepatocellular carcinoma (18); ovarian carcinoma (14); osteosarcoma (13); nasopharyngeal carcinoma (12); cervical carcinoma (10); lung adenocarcinoma (10); non-small cell lung carcinoma (10); infection (8); bladder cancer (7); Allergy (5); colitis (5); endometrial cancer (5); pancreatic cancer (5); esophageal cancer (4); liver cancer (4); cardiac hypertrophy (3); COVID-19 (3); endometriosis (3); esophageal squamous cell carcinoma (3); glioblastoma (3); laryngeal carcinoma (3); Oropharyngeal Cancer (3); psoriasis (3); retinoblastoma (3); thyroid cancer (3); allergic asthma (2); Alzheimer disease (2); colorectal adenoma (2).
A further 85 diseases each share a sentence with PTGDR in 2 papers or fewer.